AR (androgen receptor)
Diseases named in the same sentence as AR in open-access papers (continued):
Sharing a sentence is not in itself a finding about the gene and the disease.
tumor (continued). "High SF3B2 expression promotes tumor progression in CRPC by increasing the expression of androgen receptor splicing variant 7 (AR-V7) in prostate cancer." (PMID 35715826, 2022). "Here, we demonstrate that loss of AR in stromal sonic-hedgehog Gli1-lineage cells diminishes prostate epithelial oncogenesis and tumor development using in vivo assays and mouse models." (PMID 36323713, 2022). "Lastly, the close proximity of luminal progenitor cells to intermediate cells and the fact they can express AR and form neoplasia in the context of Pten loss reveal another potential source of intermediate cells." (PMID 36511483, 2022). "We functionally validated the role of oxidative phosphorylation in a panel of AR-positive cell lines and LuCaP tumor tissues, suggesting a metabolic shift towards mitochondrial metabolism associated with an aggressive form of AR-positive." (PMID 35406510, 2022). "In contrast, circulatory testosterone levels and the expression of AR in neoplastic colonic tissues showed positive associations with tumour size, advanced clinical stage, and lower survival rates in both genders." (PMID 36263327, 2022). "Our findings disclosed the expression of ERα and the ERβ variants ERβ1, ERβ2, and ERβ5 in most of tumours, whilst only a limited positivity emerged for PR and AR, consistent with previous data from us and other groups on hormone receptor status in HGSOCs." (PMID 36230510, 2022). "In case of proven efficacy, testing tumor tissues for AR would be recommended to determine potential benefit of AR-specific approaches to reduce risk of relapse." (PMID 36111296, 2022). "Late baseline T–stage, high AR/ER ratio, and high residual tumor Ki67 levels were risk factors for DFS events." (PMID 36556209, 2022). "In contrast, elevated systemic testosterone levels and higher expression of ERα and AR proteins in CRC were associated with larger tumours, poor differentiation, advanced clinical stages, and worse outcomes in both genders." (PMID 36263327, 2022). "CRPC is the lethal stage of the disease mainly driven by de novo synthesis of androgens within the tumor and other mechanisms wherein AR and its splice variants are key players." (PMID 36078112, 2022). "Supposedly, when AR signaling is more effectively suppressed, clonal selection of tumor cells will enhance AR somatic mutations, subsequently yielding aberrant transcriptomes." (PMID 36176747, 2022). "This leads to redistribution of the AR cistrome and drives tumor formation in a murine model, associated with an up-regulation in oncogenic pathways." (PMID 35682963, 2022). "Clinically used androgen receptor (AR)–targeted drugs can antagonize androgen and inhibit tumor growth, but these drugs can cause serious resistance problems." (PMID 36046733, 2022). "DNA methylation has been also implicated in regulating AR expression in AR-null cell line models and patient tumor samples." (PMID 35909568, 2022). "AR splice variants (AR-Vs) have been implicated in PC tumor progression, an increased risk of biochemical relapse, and inferior overall survival outcomes." (PMID 35650195, 2022). "Androgen receptor splice variant-7 (AR-V7) expression in circulating tumor cells (CTCs) in metastatic castration-resistant prostate cancer (mCRPC) is associated with abiraterone and enzalutamide resistance." (PMID 36289357, 2022). "PPAR-γ is implicated in tumor cell proliferation, growth invasion, and phenotypic changes in differentiation status, but also correlates with quantitative androgen receptor expression, a defining feature of LAR." (PMID 35267561, 2022). "A total of 12 DMGs were identified between the two groups, and the mutation frequency of AR, the only TF, was significantly higher in the soft tumor group than in the stiff tumor group (63.6 vs. 18.2%, p = 0.035)." (PMID 35372359, 2022).
tumor (continued). "Several genes up-regulated in patients with resistance to abiraterone and involved in tumor progression and poor survival are preferentially stimulated by AR splice variants." (PMID 35682963, 2022). "The mechanisms of acquiring therapy resistance seem to be multifaceted and often multifactorial, including AR amplifications, AR mutants and AR variants in combination with changes of intracellular signal transduction and tumour environment." (PMID 35513564, 2022). "In the tumor bodies of treated animals, 2–75 activity was associated with enhanced apoptotic induction and decreased AR nuclear accumulation." (PMID 36034650, 2022). "The luminal BC HER2 + AR+ was associated with lower histological grade, lower tumor size, higher PR expression and lower HER2 intensity of expression (2+)." (PMID 35052843, 2022). "In line with this, Wang and Koul found that loss of the canonical AR transcriptome was associated with tumor metastasis and poor clinical outcomes." (PMID 36212399, 2022). "AR positivity is shown to be associated with overexpression of HER2 in apocrine tumours, such as tumours of the mammary gland, suggesting an interaction of AR and HER2 signalling pathways in these cells." (PMID 36376977, 2022). "Several studies in PCa have evaluated AR in serum, plasma or urine, demonstrating a correlation between copy number changes, mutations and splice variants with diagnosis, prognosis, tumor evolution and outcome." (PMID 36111296, 2022). "These similarities point to the representative nature of LNCaP/V7 cells as an in vitro model of CRPC tumor cells that express AR splice variants (CRPC AR-V+)." (PMID 36139600, 2022). "This underlined the need to cautiously consider AR expression as a predictive marker for survival, according to tumor subtype." (PMID 36077653, 2022). "It is striking that the baseline and progression sample from one patient (subject 135) whose tumor underwent conversion had AR amplification despite loss of AR expression at progression." (PMID 36109521, 2022). "In this study, we investigated the role of PKLR in PCa and established the molecular basis of the tumor-promoting effects of PKLR that are associated with NEPC development after AR-targeted therapy." (PMID 35306527, 2022). "These tumours fail to respond to the first-line androgen deprivation therapies due to the loss of conventional dependency on the AR signalling for growth." (PMID 36230562, 2022). "In our study, we noticed differences with regard to tumor type, as papillary tumor cells showed a higher expression of AR-FL (full length) and AR-SVs (splice variants) than ccRCC cells." (PMID 36552000, 2022). "We demonstrate that loss of AR in stromal Shh-responsive Gli1-lineage cells diminishes prostate epithelial oncogenesis and tumor development." (PMID 36323713, 2022). "One important path is via amplification of AR so that it responds even to low levels of androgens (e.g., produced by the tumor itself); another route is via mutations of AR in a way that it becomes persistently active even in the absence of androgens." (PMID 36551650, 2022). "Overexpression of the ODC protein causes malignant transformation through activation of the androgen receptor axis, which, in turn, can affect different pathways involved in cell proliferation, cell survival, and tumor invasion." (PMID 35498409, 2022).
tumor (continued). "Androgen receptor antagonists are drugs that connect to these receptors, preventing androgens from causing tumor growth; they are administered orally daily, and include flutamide, bicalutamide, and nilutamide." (PMID 35456428, 2022). "The HER2 signaling pathway promotes the activation of a downstream pathway associated with AR-related tumor growth to induce the proliferation of the HER2+ BRCA cells." (PMID 36450882, 2022). "Until now, profiling studies of primary PCa have been focused on the most studied alterations of this tumour type, such as AR alterations, DNA copy number and single point mutations or mRNA expression." (PMID 35205419, 2022). "The changes that underlie the transition of PCa to mCRPC include, but are not limited to, inactivation of tumor suppressors, changes in antigen expression, and androgen receptor (AR) mutations." (PMID 36011027, 2022). "Repression of AR signaling and mitogen-activated protein kinases are also associated to this decreased regulation, inducing cell cycle arrest and tumor cell apoptosis, in addition to being related to drug resistance." (PMID 35456428, 2022). "The STING proinflammatory signaling cascade activated by loss of AR function can be an important determinant of tumor infiltration by immune cells." (PMID 33112375, 2021). "The selective expression of PSA over RKIP in PC is consistent with the concept that loss of AR targets with tumor suppression activities contributes to AR-promoted PC initiation and progression." (PMID 34945007, 2021). "Specifically, SNAI2 deficient tumour cells display increased sensitivity to AR signalling inhibition." (PMID 35008330, 2021). "Briefly we observed that relapsed tumors have an increase in KB content while tumor cells have reduced nuclear AR, increase of cytoplasmic AR and loss of ERG expression as compared with controls." (PMID 34584218, 2021). "Preclinical data show Niclosamide inhibits the expression of AR-V7 and lessens the resistance to LBD-targeting drugs in tumours with this variant, presumably by restoring the expression of full-length AR." (PMID 33993099, 2021). "As we have recently identified novel AR co-repressors that act as tumor suppressors, we aimed to investigate the underlying mechanism of hTERT repression by androgens." (PMID 34439179, 2021). "For example, Aggressive Variant Prostate Cancer (AVPC) presents low PSA per tumor burden, and characterized by de novo resistance to androgen receptor signaling inhibitors (ARIs)." (PMID 33903734, 2021). "Higher expression levels of AR were also associated with tumor size and lymph node (LN) metastasis (P = 0.000 and 0.006, respectively)." (PMID 33947843, 2021). "In all 6 tumours, AR immunohistochemical expression was high (positivity in > 95% of the neoplastic cells in 5/6 cases) in spite of X chromosome monosomy and AR gene loss in a variable percentage of neoplastic cells." (PMID 33534004, 2021). "In contrast, 80–90% of ER+ tumors are also AR-positive (AR+) and associated with favorable prognoses (e.g., longer relapse-free survival, lower tumor grade, and smaller tumor size), which has been confirmed in several meta-analyses." (PMID 34066328, 2021). "The mechanisms underlying AR signalling activation include the unregulated expression of androgen synthesis-related genes, intra-tumour elevated androgen, AR variants, AR gene mutation, abnormal expression of AR, and PTM." (PMID 34381019, 2021). "In rodent models, anti-androgen interventions including surgical castration, heritable mutations of the AR, and liver-specific AR-knockout reliably inhibit hepatocarcinogenesis, implicating a neoplasia-promoting capacity for AR signaling." (PMID 33574348, 2021).
tumor (continued). "Quantitation of androgen receptor variant (AR-V) expression in circulating tumor cells (CTCs) from patients with metastatic castration-resistant prostate cancer (mCRPC) has great potential for treatment customization." (PMID 34168263, 2021). "An earlier study demonstrated that LIN28A was abundantly expressed in androgen receptor-positive BC, and their coexpression positively associated with tumor grade and poor prognosis." (PMID 34572725, 2021). "Higher expression levels of AR were also associated with tumor size (Chi-square test, P = 0.000) and LN metastasis (Chi-square test, P = 0.006)." (PMID 33947843, 2021). "AR activation has also been suggested to be associated with migration, invasiveness, and metastasis of tumor cells." (PMID 34070471, 2021). "Further research with a larger sample size is needed to further examine the association between AR expression and tumor grade/subsets." (PMID 33613770, 2021). "We recently reported that suppression of AR activity in human dermal fibroblasts (HDFs) by a ligand-competitive inhibitor induces expression of a battery of tumor-promoting cancer-associated fibroblast effector genes, similarly to silencing of the gene." (PMID 33112375, 2021). "Hallmarks of SCNPC include the loss of androgen receptor (AR) expression and upregulation of neuroendocrine (NE) programs that drive tumor progression." (PMID 33471819, 2021). "Elevated AR expression, or mutations in tumor cells, causing resistance to first-generation AR antagonists, is considered the main driver of CRPC." (PMID 34948018, 2021). "We also found that the expression of the AR protein was associated with differentiated tumor grades." (PMID 33613770, 2021). "Many different mechanisms switching from androgen dependent to androgen independent tumor growth are discussed, including enhanced AR expression, AR mutations or AR evasion through other signaling pathways." (PMID 33540707, 2021). "Gains or amplifications in these regions were previously reported in TNBC tumors uncharacterized for AR status and have been associated with tumor progression." (PMID 34768979, 2021). "IQSEC1 increase occurred exclusively with androgen deprivation therapy, retained presence of tumour after therapy, and increased levels of the androgen receptor V7 variant, a major mechanism for escape from androgen deprivation." (PMID 33712589, 2021). "Some studies described an association between AR positivity and tumor progression as well as worse outcome, while other studies reported high AR expression to be associated with reduced recurrence and an improved course of disease." (PMID 34209360, 2021). "Resistance to androgen-deprivation based therapy has been attributed to AR mutations, amplifications and autocrine tumor androgen production." (PMID 36046114, 2021). "The density of the AR correlates negatively with staging and grading of the tumor, indicating that loss of androgen sensitivity is associated with tumor progression." (PMID 34206980, 2021). "miR-31, whose binding side in the AR coding region was frequently mutated in cancer, suppressed tumour formation in experimental models." (PMID 34940756, 2021). "AR variant 7 (AR-V7) is the most commonly studied variant in PCa, and its detection in circulating tumour cells (CTCs) has been described as a prognostic marker for AA and Enz resistance." (PMID 33807106, 2021). "Silencing of PRKAG2-AS1 alleviated castration-resistant prostate cancer (CRPC) tumor growth, showing repression of androgen receptor (AR) and AR variant expression." (PMID 34225739, 2021). "Most CRPC continues to depend on AR transcriptional activity to maintain tumor growth and many involve the expression of constitutively active AR splice variants (AR-Vs) that lack the LBD." (PMID 33753863, 2021). "The continued importance of the AR pathway in tumor growth and progression has been underlined by the efficacy of novel drugs targeting the AR pathway." (PMID 33974560, 2021).
tumor (continued). "Some studies indicated that tumor metabolism associated with the androgen receptor (AR) leads to the occurrence and castration resistance of PCa." (PMID 34804158, 2021). "After the discovery of glucocorticoid-activated AR mutations, the GR itself was found to possess tumor suppressor activity in PCa cells." (PMID 34137734, 2021). "Multivariate visualization did not reveal any treatment-specific markers; however, aberrant AR seemed more likely to be associated with a high tumor burden in CRPC." (PMID 34439133, 2021). "A coexpression network analysis described the TGFB1I1 mRNA which is a coactivator of the AR that is associated with PCa cell differentiation, and decreased gene expression was observed to be associated with tumor progression." (PMID 34737889, 2021). "Meanwhile, certain investigations have indicated that tumor metabolism associated with the androgen receptor (AR) leads to the occurrence and castration resistance of PCa7,8." (PMID 34795309, 2021). "This recruitment of LCoR to androgen-bound AR inhibits AR action associated with inhibition of tumor progression in xenograft tumors of CRPC cells." (PMID 33810413, 2021). "Given the notion that wild type SPOP dampens AR function in the context of ERG to sustain tumor growth, we asked if VCaP cells are particularly susceptible to increased DHT levels." (PMID 33531470, 2021). "An intriguing phenomenon associated with loss of AR signaling is the development of a neuroendocrine signature after tumor progression within the castration-resistant stage." (PMID 32685010, 2020). "Approximately 5%-30% of mutations in AR were noted in circulating tumor cells and circulating tumor DNA of CRPC patients." (PMID 35582225, 2020). "The present study further demonstrates the association of AR and Nkx3.1 with the tumor inhibitory effect of arctigenin in obese conditions." (PMID 31996731, 2020). "Patients with higher AR expression showed shorter recurrence-free survival, indicating a positive association between AR expression and tumor progression." (PMID 32292603, 2020). "A hallmark of PCa is the dependency on AR signaling pathways for tumor progression illustrated by the increased abundance of AR amplification." (PMID 33747899, 2020). "Pathological features associated with AR negativity included tumour necrosis involving > 50% of the tumor and a prominent lymphoid infiltrate at the tumour margin." (PMID 32928183, 2020). "Most ER-positive breast tumors express ARs, and AR expression in ER-positive cases is associated with smaller tumor size, lower Nottingham grade, and less frequent tumor cell necrosis." (PMID 32326308, 2020). "In the first 7 years post-diagnosis, AR expression was associated with a 62% increase in BC-specific mortality in patients with ER-tumors after adjustments for patient, tumor, and treatment covariates." (PMID 32429078, 2020). "In the 123 triple-negative FMCs, Sox2 expression showed a positive association with the clinical tumor size, dermal infiltration, the Ki-67 proliferation index, AR expression, and intratumoral Treg numbers." (PMID 33553286, 2020). "In BC, the AR-V7 variant was shown to be commonly expressed in primary BC tumor tissue and BC cancer cell lines, providing evidence to promote growth and mediate resistance to AR inhibitory treatment." (PMID 33014830, 2020). "In this study, a high AR status was significantly associated with favorable clinicopathologic features such as small tumor size and low histologic grade." (PMID 32290220, 2020). "Ack1 is a kinase implicated in the phosphorylation of pTyr267-AR, which is critical to androgen-independent AR transactivation and tumor promoting." (PMID 32293453, 2020). "Variant from of activated AR, AR-V7, has been shown to significant upregulation in tumor tissues, and shown to promote drug resistance." (PMID 31896509, 2020).